IL13RA1 (interleukin 13 receptor subunit alpha 1)
Diseases named in the same sentence as IL13RA1 in open-access papers (continued):
Sharing a sentence is not in itself a finding about the gene and the disease.
ulcerative colitis (3 papers, 2018 to 2022). An inflammatory bowel disease involving the mucosal surface of the large intestine and rectum. "MD3 was upregulated in human ulcerative colitis and MD3 expression could be increased in HT-29/B6 cells by IL-13 via the IL13Rα1/STAT pathway." (PMID 35563847, 2022).
adenoma (2 papers, 2020 to 2023). A neoplasm arising from the epithelium. "Previously, IL-13Rα1 protein expression has been demonstrated in the colon, in both adenomas and adenocarcinomas." (PMID 32512917, 2020).
clear cell renal cell carcinoma (2 papers, 2021 to 2022). "Previously we reported that IL4Rα and IL13Rα1 (Type II receptor) is a prognostic marker and involved in the development of clear cell renal cell carcinoma (ccRCC) through JAK2/FOXO3 pathway." (PMID 35207737, 2022). "Especially, clear cell renal cell carcinoma patients with co-positivity for the expression of IL4Rα and IL13Rα1 had the shortest survival time." (PMID 33419470, 2021). "Consistently, although nuclear and cytoplasmic expression were not analyzed separately, higher expression of IL4Rα and IL13Rα1 were significantly associated with shorter cancer-specific survival and RFS of clear cell renal cell carcinoma patients." (PMID 33419470, 2021).
Granuloma (2 papers, 2021 to 2025). A compact, organized collection of mature mononuclear phagocytes, which may be but is not necessarily accompanied by accessory features such as necrosis. "Our upstream pathway analysis of CSF1R identified IL4R as a regulated gene, corroborating the literature linking interleukin-4 receptor alpha (IL4RA) and interleukin-13 receptor alpha 1 (IL13RA1) signaling to granuloma." (PMID 40521183, 2025). "Additionally, we observed an enhanced expression of IL13Rα1, Jak3, and STAT6 in macrophages within CS granulomas and the increased phosphorylation of Jak3 and STAT6 are indicative of an activation of anti-inflammatory IL4/IL13 signaling pathways." (PMID 40521183, 2025).
heart failure (2 papers, 2018 to 2023). Inability of the heart to pump blood at an adequate rate to meet tissue metabolic requirements. "Interestingly, despite IL-13 gene tended to be upregulated, the IL-13 receptor subunit alpha 1 (IL-13Rα1) production was significantly decreased in the same cardiac muscle specimens of T2D patients with heart failure, who are by definition insulin-resistant." (PMID 29675435, 2018). "Stimulation of IL-13RA1/STAT3 signaling can induce the excessive accumulation of included extracellular matrix, cardiac fibrosis, chronic cardiac stress, and heart failure." (PMID 36978012, 2023).
Hepatic fibrosis (2 papers, 2017 to 2022). The presence of excessive fibrous connective tissue in the liver. "The IL-13Rα1 signaling pathway and M2 macrophages play crucial roles in schistosome egg-induced hepatic fibrosis via the expression of pro-fibrotic molecules." (PMID 29094025, 2017). "In conclusion, corilagin can suppress schistosome egg-induced hepatic fibrosis via inhibition of M2 macrophage polarization in the IL-13Rα1 signaling pathway." (PMID 29094025, 2017). "This study aims to investigate the inhibitory effect and mechanism of action of corilagin on schistosome egg-induced hepatic fibrosis via the IL-13Rα1 signaling pathway in M2 macrophages in vitro and in vivo." (PMID 29094025, 2017). "In this study, we demonstrated the inhibitory effect of corilagin on M2 macrophages and schistosome-egg-induced hepatic fibrosis via IL-13Rα1 signaling pathway in vitro and in vivo, especially after the adult schistosomes were killed." (PMID 29094025, 2017). "IL-13Rα1 is a central mediator of the Th2-biased response and schistosomiasis hepatic fibrosis." (PMID 29094025, 2017). "Thus, inhibition of M2 polarization of macrophages and IL-13Rα1 signaling pathway may be the key to suppressing schistosomiasis hepatic fibrosis." (PMID 29094025, 2017). "Among those, IL-13Ra1 was the most significantly and differentially expressed protein in PSC-derived EVs and correlated with the degree of liver fibrosis." (PMID 35194091, 2022).
Hodgkins lymphoma (2 papers, 2023 to 2025). A heterogeneous group of malignant lymphoid neoplasms of B-cell origin characterized histologically by the presence of Hodgkin and Reed-Sternberg (HRS) cells in the vast majority of cases. "The most important genes in Hodgkin’s lymphoma (HL) encode proteins implicated in signal transduction: interleukin-13 receptor subunit alpha-1 (IL13RA1) and its direct partners, STAT6 and IL4R." (PMID 37297004, 2023).
Insulin resistance (2 papers, 2017 to 2022). Increased resistance towards insulin, that is, diminished effectiveness of insulin in reducing blood glucose levels. "• Polarization of macrophages into an M2 profile through the IL-13Rα1/IL-4R receptor. • Decrease insulin resistance. • Involved in increasing inflammation via the NLRP3 inflammasome. • Increases fatty acid oxidation in muscle." (PMID 35422689, 2022).
invasive breast carcinoma (2 papers, 2021 to 2024). A carcinoma that infiltrates the breast parenchyma. "In contrast, high IL-13Rα1 expression was significantly associated with clinicopathological parameters of aggressive phenotypes and with reduced survival in patients with invasive breast cancer." (PMID 33591997, 2021).
lupus (2 papers, 2022 to 2025). "IL-13Rα1 has also been implicated in additional aspects of B cell homeostasis, such as the expansion of age-associated/autoimmune B cells in lupus." (PMID 40614216, 2025).
lymph node metastasis (2 papers, 2019 to 2022). "Age of patients, serum level of CA19-9, tumor stage, T category, lymph node metastasis, distant metastasis, histologic type, histologic grade, Nu-IL4Rα, Cy-IL4Rα, Nu-IL13Rα1, and Cy-IL13Rα1 were included in multivariate analysis." (PMID 35207737, 2022). "The factors significantly associated with both cancer-specific survival (CSS) and relapse-free survival (RFS) in univariate survival analysis, were sex, age of patients, tumor size, tumor stage, lymph node metastasis, and immunohistochemical expressions of IL4Rα and IL13Rα1." (PMID 31540495, 2019).
metastasis (2 papers, 2019 to 2025). The spread or migration of cancer cells from one part of the body (where they first appeared) to another. "This subgrouping for the co-expression patterns of IL4Rα and IL13Rα1 was significantly associated with age (p = 0.007), tumor size (p = 0.029), tumor stage (p = 0.027), and lymph node metastasis (p = 0.017), and significantly associated with CSS (Log-rank, p < 0.001)and RFS (Log-rank, p < 0.001)." (PMID 31540495, 2019). "Changes in IL13RA1 may reflect altered IL4 receptor activity, especially in bone metastasis tumor cells." (PMID 39941924, 2025).
schistosomiasis (2 papers, 2009 to 2017). An infectious disease caused by parasitic trematodes of the genus Schistosoma that colonize human blood vessels and release eggs that can cause granulomatous reactions leading to acute (swimmer's itch or acute schistosomiasis syndrome) or chronic disease. "Because production of the soluble IL-13Rα2 is IL-4Rα-, IL-13Rα1-, and Stat6-dependent, these data combined with the schistosomiasis studies suggested that the Retnla−/− mice were developing stronger IL-4/IL-13 responses following infection." (PMID 19381262, 2009).
Sepsis (2 papers, 2024 to 2025). Sepsis is defined as life-threatening organ dysfunction caused by a dysregulated host response to infection. "Similar to those in skeletal muscles of sepsis mice, expression of Mb, Tnni1, and Myh7 mRNAs was downregulated, while that of IL‐13RA1 was upregulated in LPS‐stimulated C2C12 myotubes." (PMID 39016179, 2024). "Of note, mRNA and protein expression levels of IL‐13Rα1 in both WT and PD‐1 KO skeletal muscle were upregulated by sepsis." (PMID 39016179, 2024). "Interestingly, our present data exhibit a significant increase in mRNA and protein of IL‐13Rα1 in skeletal muscle after severe sepsis." (PMID 39016179, 2024).
soft tissue sarcoma (2 papers, 2021 to 2022). A malignant neoplasm arising from muscle tissue, adipose tissue, blood vessels, fibrous tissue, or other supportive tissues excluding the bones. "In human soft-tissue sarcomas, immunohistochemical expression of IL4Rα was significantly associated with IL13Rα1 expression." (PMID 33419470, 2021). "Nuclear and cytoplasmic expression of IL4Rα and IL13Rα1 were significantly associated with shorter survival of soft-tissue sarcoma patients in univariate analysis." (PMID 33419470, 2021). "This study suggests IL4Rα and IL13Rα1 are associated with the progression of soft-tissue sarcoma, and the expression of IL4Rα and IL13Rα1 might be novel prognostic indicators of soft-tissue sarcoma patients." (PMID 33419470, 2021). "Higher expression of IL13Rα1 was also presented as an indicator of poor prognosis of breast cancer, renal cell carcinoma, soft-tissue sarcomas, and glioblastoma." (PMID 35207737, 2022). "This study investigated the immunohistochemical expression of IL4Rα and IL13Rα1 in 89 soft-tissue sarcomas of the extremities, superficial trunk, and retroperitoneum." (PMID 33419470, 2021). "Moreover, the co-expression pattern of nuclear IL4Rα and IL13Rα1 was an independent indicator of shorter survival of soft-tissue sarcoma patients (overall survival; overall p < 0.001, relapse-free survival; overall p < 0.001)." (PMID 33419470, 2021). "Multivariate analysis indicated that nuclear expression of IL4Rα and IL13Rα1 were independent indicators of shorter overall survival (IL4Rα; p = 0.002, IL13Rα1; p = 0.016) and relapse-free survival (IL4Rα; p = 0.022, IL13Rα1; p < 0.001) of soft-tissue sarcoma patients." (PMID 33419470, 2021). "However, studies on IL4Rα and IL13Rα1 in soft-tissue sarcomas have been limited." (PMID 33419470, 2021). "Furthermore, in a previous study evaluated for the prognostic significance of the expressions of IL4Rα and IL13Rα1 according to their subcellular localization, both nuclear expressions of IL4Rα and IL13Rα1 were the independent indicators of shorter OS and RFS of soft tissue sarcoma patients." (PMID 35207737, 2022).
Stroke (2 papers, 2014 to 2022). Sudden impairment of blood flow to a part of the brain due to occlusion or rupture of an artery to the brain. "Likewise, interleukin 13 receptor, alpha 1 (Il13ra1) gene encoding a receptor on SMCs and fibroblasts and which is also a new player for stroke scholars, may promote fibrosis by inhibiting metalloprotease activity in fibroblasts." (PMID 24672479, 2014). "In the current study, we demonstrated that IL-13Rα1 was mainly expressed on microglia/macrophages and neurons under both physiological and under stroke conditions, with hardly any expression on oligodendrocyte." (PMID 35578342, 2022). "Immunofluorescence staining also showed co-labeling of IL-13Rα1 and microglia/macrophage (Iba1+) in the peri-infarct cortex and striatum 3 days after tMCAO, indicating the express of IL-13Rα1 on morphologically activated microglia/macrophage after stroke." (PMID 35578342, 2022). "Our results suggested that IL-13Rα1 might play a key role in the stroke brain, especially in microglia/macrophages." (PMID 35578342, 2022).
angiosarcoma (1 paper, 2025). A malignant tumor arising from the endothelial cells of the blood vessels. "In contrast, IL-13Rα1 expression was limited in the angiosarcoma cell line, indicating a distinct pattern of high IL-13Rα2 and low IL-13Rα1 expression in angiosarcoma." (PMID 40855097, 2025). "Importantly, our findings revealed that angiosarcoma cell lines exhibited much lower IL-13Rα1 expression compared to neutrophils and other peripheral T and B cells." (PMID 40855097, 2025).
Arthritis (1 paper, 2020). Inflammation of a joint. "The inhibitory effects of IL13Rα1 on arthritis progression suggest the therapeutic potential in RA." (PMID 32771038, 2020). "Collectively, these data support that IL13Rα1 plays an anti-arthritis role in RA." (PMID 32771038, 2020).
atherosclerosis (1 paper, 2022). A disease characterized by the build-up of fatty material and calcium deposition in the arterial wall resulting in partial or complete occlusion of the arterial lumen. "We verified 4 genes of them to have a strong correlation with CAD, and IL13RA1 might participate in the inflammation, fibrosis, and cholesterol efflux process of atherosclerosis by regulating JAK1/STAT3 pathway." (PMID 36064568, 2022). "We further uncovered the role of IL13RA1 might play in atherosclerosis." (PMID 36064568, 2022).
Autoimmunity (1 paper, 2022). The occurrence of an immune reaction against the organism's own cells or tissues. "During an antigen rechallenge, rapid production of IL-4 occurs, which causes apoptosis of neonatal Th1 cells through the formation of heteroreceptor IL-4Rα/IL-13Rα1, which together with regulatory T cells takes part in the control over peripheral tolerance and restrains autoimmunity in adults." (PMID 36619667, 2022).
colitis (1 paper, 2019). Inflammation of the colon. "In acute DSS colitis and after 1 cycle of administration of DSS, IL-13RA1 mRNA expression was lower than in the controls, but normalized after further DSS cycles." (PMID 31296924, 2019).
coronary heart disease (1 paper, 2024). "This study focuses on four biomarkers C5orf58, ZNF180, CTAG1A, and IL13RA1 that are associated with M1 macrophage polarization and bubble cell proliferation in coronary heart disease, highlighting their key roles in the pathogenesis of the disease." (PMID 39723414, 2024). "This study focuses on the roles of C5orf58, ZNF180, CTAG1A, and IL13RA1 in the polarization of M1 macrophages and the increase of bubble cells in coronary heart disease." (PMID 39723414, 2024). "This indicates that the biomarker IL13RA1 identified in this study may play an important regulatory role in the occurrence and development of coronary heart disease." (PMID 39723414, 2024).
dementia (1 paper, 2025). Loss of intellectual abilities interfering with an individual's social and occupational functions. "Utilizing the dataset (Synapse ID: syn5550404) derived from entorhinal cortex and cerebellum of healthy, AD, Progressive supranuclear Palsy (PSP), and ‘Pathologic Aging’ human subjects that have Aβ without dementia, we found IL13RA1 levels increased in AD patients." (PMID 40055831, 2025).
dilated cardiomyopathy (1 paper, 2017). Cardiomyopathy which is characterized by dilation and contractile dysfunction of the left and right ventricles. "Remarkably, the expression of the chains comprising type‐2 IL‐4R, Il13ra1 and Il4ra were downregulated in the failing hearts of patients with ischemic and dilated cardiomyopathy, compared with controls." (PMID 28528324, 2017).
Dupuytren’s disease (1 paper, 2020). "Here, we report immune cell–driven IL-13 production and signaling in Dupuytren’s disease, which enhances the fibroproliferative features of the tissue response primarily through increased IL-13Rα1 signaling." (PMID 32695877, 2020). "By chromatin immunoprecipitation (ChIP), we also show enriched signal transducer and activator of transcription 1 (STAT1) binding at the IL-13Rα1 site that drive the enhanced fibrotic response in Dupuytren’s disease." (PMID 32695877, 2020). "S3A) has a key role in manifesting the enhanced effects of IL-13 via up-regulation of IL-13Rα1 in Dupuytren’s disease, we investigated whether differential STAT1 binding at the IL-13Rα1 gene locus may cause this to enhance its activity by performing ChIP enrichment analysis." (PMID 32695877, 2020).
encephalitis (1 paper, 2022). An acute inflammatory process affecting the brain parenchyma. "Pathways associated with SOCS1, SHIP1, C/EBP-β, and IL13Rα1 signaling cascades might regulate the development CASPR2 encephalitis but not LGI1 encephalitis." (PMID 35083659, 2022).
endotoxemia (1 paper, 2010). "IL-13RA1 mediates translational repression of TNF-α mRNA in LPS-stimulated monocytes and is required for IL-13-mediated protection of mice from lethal endotoxemia." (PMID 20105294, 2010).
esophagitis (1 paper, 2021). An acute or chronic inflammatory disease affecting the esophageal wall. "It was reported that a monoclonal antibody against IL13 prevented its binding to IL13Rα1 and IL13Rα 2 and inhibited esophagitis progression." (PMID 34652890, 2021).
food allergies (1 paper, 2025). "Moreover, IL13RA1 expression in RNA-seq data from B cells isolated from adolescents with or without IgE-mediated food allergies was significantly higher in male than in female B cells." (PMID 40614216, 2025).
gallbladder carcinoma (1 paper, 2022). "This prognostic significance of Nu-IL4Rα-positivity presents the expression pattern of IL4Rα and IL13Rα1 is used as prognostic indicators of gallbladder carcinoma patients." (PMID 35207737, 2022). "We demonstrated that the downregulated IL4Rα or IL13Rα1 caused apoptosis in SNU308 gallbladder cells and investigated the anti-carcinogenic effect of AZD1480, a JAK2 inhibitor, in human gallbladder carcinoma SNU308 cells." (PMID 35207737, 2022). "In conclusion, this study showed the expression of IL4Rα and IL13Rα1 was used as a potential prognostic marker of gallbladder carcinomas and presented nuclear expression of IL4Rα as an independent indicator of shorter OS and FRS." (PMID 35207737, 2022). "In univariate survival analysis, nuclear or cytoplasmic expressions of IL4Rα and IL13Rα1 were significantly associated with shorter OS and RFS of gallbladder carcinoma patients." (PMID 35207737, 2022). "This study evaluated the expressions of IL4Rα and IL13Rα1 in human gallbladder carcinomas and presented IL4Rα/IL13Rα1 pathway is involved in the progression of gallbladder carcinomas." (PMID 35207737, 2022). "Taken together, in human gallbladder carcinoma tissue, we found a statistically significant association between the expression IL4R and IL13Rα1 and poor prognostic properties by analyzing tissue microarray." (PMID 35207737, 2022). "This study also presented that nuclear expression of IL4Rα and IL13Rα1 was involved in pathogenesis important in the progression of gallbladder carcinomas." (PMID 35207737, 2022). "Immunohistochemically, IL4Rα and IL13Rα1 were expressed in cytoplasm and nuclei of gallbladder cancer cells." (PMID 35207737, 2022). "Therefore, the result of this study suggests the expressions of IL4Rα and IL13Rα1 as novel prognostic indicators of gallbladder carcinoma patients." (PMID 35207737, 2022). "However, the expressions of IL4Rα and IL13Rα1 were dominant on cytoplasm and nuclei in gallbladder cancer cells." (PMID 35207737, 2022). "However, the role of IL4Rα and IL13Rα1 signaling pathway has not been fully understood in the development of gallbladder cancer." (PMID 35207737, 2022). "The potential prognostic clinicopathologic factors and the expressions of Nu-IL4Rα, Cy-IL4Rα, Nu-IL13Rα1, and Cy-IL13Rα1 were evaluated for their impact on OS and RFS of gallbladder carcinoma patients." (PMID 35207737, 2022). "After knockdown of IL4Rα or IL13Rα1, cell assays to measure the proliferation and apoptosis and Western blotting analysis were conducted in SNU308 human gallbladder cancer cells." (PMID 35207737, 2022). "However, the exact effects of IL4Rα or IL13Rα1 in gallbladder cancer development have not been studied." (PMID 35207737, 2022). "Therefore, our findings suggests that the IL4Rα and IL13Rα1 complex and JAK2 signaling pathway could be efficient therapeutic targets for gallbladder cancer treatment." (PMID 35207737, 2022).
Glucose intolerance (1 paper, 2025). Glucose intolerance (GI) can be defined as dysglycemia that comprises both prediabetes and diabetes. "Our published work on Il13-KO and the current study demonstrate that mice lacking whole-body or preadipocyte IL-13/IL13Rα1 signaling show increased weight gain and glucose intolerance." (PMID 40198135, 2025).
head and neck cancer (1 paper, 2019). A primary or metastatic malignant neoplasm affecting the head and neck. "IL13Rα1 is an important to target of cancer therapy in human head and neck cancer animal models." (PMID 31540495, 2019).